IL1B (interleukin 1 beta)
Diseases named in the same sentence as IL1B in open-access papers (continued):
Sharing a sentence is not in itself a finding about the gene and the disease.
infection (continued). "When analyzing pro-inflammatory cytokine gene expression, we observed a significant increase in gene expression at d7 p.i. of IL-1β and IFNγ with no change of TNF or iNOS expression in p.o. infected mice when compared to i.p. infection." (PMID 35898505, 2022). "NAIP-/- and NLRC4-/- THP-1s treated with CASP5 siRNA showed a slight but significant decrease in IL-1β secretion following CASP5 siRNA treatment, but not CASP4 siRNA treatment, compared to control siRNA-treated cells following WT Stm infection." (PMID 35073381, 2022). "IL-1β, TNF-α, CXCL1, and CXCL2 were significantly decreased in fibrotic mice compared with nonfibrotic mice after infection, both at the protein and mRNA levels." (PMID 34990413, 2022). "We observed that there was a significantly higher level of IL-12 and IFNγ at 7 d.p.i. upon i.p. infection and nominally, but non-significantly, higher expression of TNF and IL-1β." (PMID 35898505, 2022). "Significantly higher levels of IL-17, IL-1β, IL-6 and TNF-α were detected in BAL and lung tissue lysates from infected CS-exposed mice, compared to non-infected animals at 24h after infection." (PMID 33784296, 2021). "Our findings in serum support and expand on this, as nearly every cytokine and chemokine involved with a cell-mediated response (MIP-2, MIP-3α, MCP-1, IL-1β, IP-10, TNF-α) was significantly elevated in the CF mouse, even without detectable infection." (PMID 34475490, 2021). "Here, we report that IL-1β release in THP-1 macrophages is significantly increased in response to heat-killed Y. enterocolitica treatment and ΔyopBY. enterocolitica infection, but not in wild-type Y. enterocolitica infection." (PMID 34319170, 2021). "In human macrophages, gene expression levels for IL‐1β, IL‐18, and TNF‐α from WT infections remained low and were never two‐fold higher than uninfected macrophages." (PMID 33970545, 2021). "Consistent with a chronic inflammatory state, the serum levels of pro-inflammatory cytokines such as TNFα, IFNγ, and IL-1β increased as a result of the infection in the WT and FPR2-/- mice, although the IL-1β increase in the FPR2-/- mice was not significant." (PMID 34784372, 2021). "This correlated with a decrease in inflammatory cytokine expression (Il1b, Tnf, and Il6) by DIO Mφs given IFNβ during MHV-A59 infection compared to infected DIO BMDMs not treated with IFNβ." (PMID 34479991, 2021). "Low levels of human IL‐1β and TNF‐α were recovered from WT, LVS, and clcA mutant infection supernatants, but were not considered physiologically relevant (<10 pg/ml for all strains, Figure A6E‐F)." (PMID 33970545, 2021). "However, there were no significant changes in serum IL-6, TNF-α, and IL-1β levels under the same condition; moreover, we did not observe any reductions in damage to the lungs and kidneys (organs that are vulnerable to severe infection) in CdCl3-pretreated mice after CLP." (PMID 33564275, 2021). "At early time points, Fpr2-/- mice showed a significant decrease in CXCL1, CXCL2, IL-1β, CCL2, GM-CSF, IL-6, and CCL3 levels at 1 hour and 3 hours after infection, and an increase in IL-22 and IL-23, but there is no change in TNF-α, as compared with WT mice." (PMID 34899755, 2021). "Unlike the pattern observed in the liver, only splenic caspase-1, IL-1β, and GSDMD increased during S. mansoni infection; whereas levels of NLRP3 and IL-18 did not increase during infection." (PMID 34161342, 2021). "Untreated animals showed elevated levels of IL-6 and IL-10 but not IL-1β and TNF-α, in their lungs 4 days after the infection." (PMID 34648602, 2021). "Our previous study demonstrated that in response to infection with Gram-negative bacteria, THP-1 macrophages produce PGE2, critical for IL-1β increase." (PMID 34319170, 2021). "Collectively, these results suggest that induction of cell death by the ΔpknF mutant was independent of GSDMD and ΔpknF mutant infection results in both GSDMD-dependent and -independent secretion of IL-1β." (PMID 34324582, 2021).
infection (continued). "In the absence of maltol, infection (NC group) with E. maxima increased (P < 0.05) the gene expression of TNFSF15 (3.4 × 10−3-2.3 × 10−2), IL-1β (1.9 × 10−3-4.9 × 10−3), and IL-6 (3.0 × 10−3-9.9 × 10−3) in the distal jejunum compared to that of the CON group." (PMID 34095279, 2021). "Since the growth of biofilms was generally tolerated by the skin, it is worth noting that, at the end of the 3-day infection, MRSA-lux did not induce any increased cytotoxic effects or significant IL-1β and IL-8 release when compared to the uninfected control." (PMID 33495449, 2021). "Experimental infection in rodents with various strains of P. gingivalis have been shown to increase maternal serum levels of TNF, IFN-γ, and IL-1β along with FGR10,13,15, which we did not see in our model." (PMID 32884071, 2020). "The levels of IFN-γ, TNF-α and IL-1β, but not IL-2, at MGAS5005, MGAS315, and MGAS6180 infection sites were higher in SseM1-immunized mice than in control mice." (PMID 32308652, 2020). "infection of SCC cells did not affect mRNA levels of IL10, IL1β, IL1α, HBEGF, and GMCSF, compared with NS cells." (PMID 31912662, 2020). "Increased levels of IL-1β, IL-6, and TNFα were detected in sera of PLGA-PEG-treated mice both in the presence and absence of C. albicans-infection (respectively)." (PMID 33091017, 2020). "Even though P2X7R activation appears to enhance IL-1β production through the noncanonical NLRP3 in vitro, its participation in the control of in vivo infection by L. amazonensis has not been addressed." (PMID 33061823, 2020). "ELISA of oral tongue tissues (MOIL) 2 days after infection showed that while infection promoted the expression of IL-1β in MOIL of young mice, cells derived from aged MOIL produced little or no IL-1β." (PMID 33240286, 2020). "Infection with B. abortus at MOI 100 and 1,000 induced IL-6 but not IL-1β nor TNF-α (not shown) secretion by both pre-adipocytes and adipocytes." (PMID 33071987, 2020). "The expression levels of IL-1β and CCL11 in the infection group were lower than those of the non-infected group at 48 hours post-infection, suggesting that these genes were strongly suppressed by tetrathyridium infection." (PMID 33048942, 2020). "However, during EAEC infection, proinflammatory cytokines could enhance mucus secretion through enterocytes, since among the E. coli pathotypes, EAEC is the best inducer of TNF-α secretion in epithelial cells and induces the secretion of TNF-α, IL-6, or IL-1β by macrophages." (PMID 33281812, 2020). "Consistent with previous findings, LCMV-infected WT mice showed a significant increase of CCL2 on day 3 postinfection and IL-5 on day 7 postinfection, only, while TNF, IL-1β, IL-6, IFN-γ, CCL1 and CCL22 levels did not change following infection." (PMID 32310998, 2020). "At 24 h post-infection, the mRNA level of TNF-α, IL-1β, and IL-6 were measured by relative quantitative RT-PCR normalized against peptidylprolyl isomerase A (PPIA), a molecule that has been previously used for internal control." (PMID 31561412, 2019). "Early after infection, TNFα, IL6 and IL12p40, but not IL1β, remained present at significantly higher levels in BAL cell supernatants from cynomolgus macaques." (PMID 31736945, 2019). "When IL-1β production was tested in THP-1 cells, infection with the type II T. gondii strain, but not the type I or type III strains, induced IL-1β production in THP-1 cells as previously reported." (PMID 31119110, 2019). "The amniotic fluid concentrations of some inflammasome mediators (CASP1, IL1B, NLRP3, and IL18) are greater in women who have spontaneous preterm or term labor with intraamniotic infection/inflammation than in those without this clinical condition." (PMID 30935390, 2019). "Ex vivo analyses of monocytes demonstrated upregulation of interleukin-1 beta (IL-1β) and tumor necrosis factor alpha (TNF-α) mRNA and increased nitric oxide production during T. parva lethal infection compared to nonlethal infection at 10 dpi." (PMID 31570561, 2019).
infection (continued). "VEGF and IFN-γ also did not have altered expression upon infection, and many samples did not have detectable amounts of IFN-γ, TNF-α, IL-1α, or IL-1β (data not shown)." (PMID 31289185, 2019). "Here, we showed that increased IL-1β response induced by c-di-AMP and rBCG-DisA infection in RAW264.7 macrophages, but not in BCG-infected cells." (PMID 31333655, 2019). "Next, MNV infections in primary macrophages lacking both caspase-1 and -11, or lacking the adaptor protein ASC demonstrated that MNV induced maturation and secretion of IL-1β in an ASC- and caspase-1-dependent manner." (PMID 31017981, 2019). "In brief, induction of organ homogenate cytokine production was low or not increased in response to infection (tumor necrosis factor alpha [TNF-α] and IFN-γ), except for interleukin 1β (IL-1β), which largely reflected organ bacterial loads." (PMID 31822597, 2019). "In comparison, the expression of IL-1β, TNF-α, and IL-6 is not markedly changed 12 h after infection, which is markedly increased 24 h and 48 h after infection." (PMID 30186539, 2018). "We unequivocally show that ISG15 production during Toxoplasma infection results in the recruitment of CD8α+ dendritic cells (DCs) to the site of infection and that ISG15 exclusively stimulates IL-1β and not IL-12 production by CD8α+ DCs." (PMID 29891555, 2018). "Addition of isotype control antibody, anti-IL-1β, IL-6, or IL-10 antibodies did not significantly affect the generation of T cells expressing IFN-γ or TNF-α during in vitro infection and T cell priming." (PMID 30233599, 2018). "In a previous study investigating the direct infection of human macrophages with Mtb, other stimuli such as LPS, BCG, and individual cytokines including TNF‐α, IL‐1β or IFN‐γ did not drive MMP‐1 production." (PMID 29210073, 2018). "In BATF3−/− mice lacking CD8α+ DCs, ISG15 fails to induce an IL-1β increase during Toxoplasma infection, as seen in B6 mice, demonstrating that ISG15 induces IL-1β–producing CD8α+ DCs at the site of infection." (PMID 29891555, 2018). "Tlr4−/− and Il1b−/− mice showed an attenuated phenotype, with markedly reduced background NK1R/SP expression and little or no response to infection." (PMID 30030504, 2018). "In HepG2 with infection of ATCC 43251 + 0.5 μmol/L DPI treatment, the expression of TNF‐α is decreased about 26.7% and the expression of IL‐1β is increased about 29.4% comparing with that of without DPI treatment." (PMID 30258592, 2018). "Significantly, we show that IL-1β treatment of bone marrow-derived DCs (BMDCs) results in induction of IFN-β and ISGs at late time points posttreatment and in the absence of infection." (PMID 29559569, 2018). "Immunoblot analysis revealed that IL-1β maturation occurred in response to ΔnleF, but not EDL933 (or ΔnleF/nleF) infection, suggesting that ΔnleF infection induced pyroptosis-like cell death." (PMID 28593173, 2017). "IL-1β, IL-6, IL-8, and IL-12 mRNA expression were also increased in Ab4 infected EREC, whereas no modulation was described after PBMC infection." (PMID 28925977, 2017). "Whereas IFN-γ, IL-1β, IL-10, IL-12/IL-23p40, IL-17A, KC and MIG were not produced after infection or LPS-stimulation, elevated MCP-1 levels were measured only at 72–96 h (data not shown)." (PMID 28697801, 2017). "ELISA analyses revealed that CSF3, IL-1β, and IL-6 proteins were induced by EV71 or R848 (a TLR7 agonist) as a stimulus control, but not by mock-infection or UV-inactivated EV71, in THP-1, macrophages, and human PBMCs." (PMID 28854257, 2017). "TLR2-deficient mice have reduced Il-1β expression compared to WT at 6 h post-infection with Staphylococcus aureus, but not at 24 h41, suggesting that the role of TLR2 in IL-1β production is most significant in the early stages of infection." (PMID 28824166, 2017).
infection (continued). "In the present study, however, neutrophil accumulation and TNF-α, IL-1β, IL-17A and MIP-2 synthesis in the lungs after infection with S. pneumoniae were not significantly different between WT and Dectin-2KO mice." (PMID 26727976, 2016). "We observed a progressive elevation of serum cytokine and chemokine levels including IL-6, IL-1β, IFN- α, IFN- γ, IL-17, and IL-1Ra beginning 24 h post-infection; only IL-12p40 was not elevated." (PMID 27855182, 2016). "Although YopM inhibits a pathway dependent on Asc and caspase-1, we observed no decrease of IL-1β in cells lacking NLRP3, NLRC4, or caspase-11 compared to wild-type cells after infection with Y. pestis lacking YopM." (PMID 27911947, 2016). "Other cytokines and chemokines, such as IL-1β, IL-10, IL-17, TNF-α, IFN-γ, RANTES, and EOTAXIN, were also upregulated in the serum upon infection, but to a relatively lesser extent (data not shown)." (PMID 27756321, 2016). "It is difficult to determine the usefulness of other cytokines, where IFN-γ and IL-10 were elevated late in the infection and the TNF-α, IL-1β, and IL-12p70 cytokines were randomly elevated and did not respond to oseltamivir." (PMID 27110056, 2016). "HGPg-induced IL-1β in medium was inhibited by cells pretreated with LY294002 and rapamycin, as was infection with DN-Akt, but not by treatment with vehicle controls." (PMID 28083517, 2016). "On the contrary, ΔYopM/YopM rescue strain infection triggered increased HMGB1 release without inducing caspase-1 cleavage and IL-1β secretion." (PMID 27929533, 2016). "No significant variations were observed for IL-1β and TNF-α expression in the acute infection model even if a trend for increase was observed for both the cytokines mRNAs in the presence of S. aureus after 9 h." (PMID 27446812, 2016). "Non-egg or low egg intensity infections (SmPCR+) on the other hand revealed a unique profile of elevated SEA-specific IgG4 with decreased systemic IL-2 and IL-1β." (PMID 27152725, 2016). "Silencing of H2B, cGAS and STING inhibited IFN-β induction but not IL-1β secretion, and cGAMP activity is significantly reduced by H2B and IFI16 knockdown during infection." (PMID 27764250, 2016). "We found a significant increased production of IL-1α and IL-1β, but not IL-18, and of the cleaved fragment of procaspase-1 in the lungs of Cftr–/– than C57BL/6 mice during either infection." (PMID 26972847, 2016). "At 30 h post infection, IL-10 and KC levels were lower in C/EBPδ−/− brain homogenates, whereas brain IL-6, TNF-α, IL-1β, and MIP-2 levels were not significantly different between the two genotypes." (PMID 25958220, 2015). "Although elevated expression of IL-1β was observed with in vitro EBOV infection, IL-1β was not similarly induced following in vitro infection with BDBV." (PMID 26512687, 2015). "After infection, CD1c+ DCs expressed HLA-DR, CD40, and CD83 (top) and produced IL-6, TNF-α, and IL-1β but not IL-23, TGF-β, or IL-12p70 (F and data not shown)." (PMID 25071784, 2014). "In the brain, the expression level of NLRP3 and IL-1β in VK627 group increased rapidly while rVK627E infection not, this suggested that VK627 infection can activate the inflammatory processes of brain quickly while rVK627E infection can not." (PMID 25547136, 2014). "Infection with L. major increased the secretion of TNF-α, IL-6, TIMP-1, IL-1RA, G-CSF and TREM, but not IL-1α or IL-1β." (PMID 24416445, 2014). "Although there was a trend for elevated levels of IL-1β, IL-6, and MCP-1 in CPEfat/fat mice 24 h post infection, none of these differences reached statistically significance." (PMID 25203099, 2014). "However, the proinflammatory cytokines TNF-α and IL-1β had no decreasing effects on virus replication, suggesting that these cytokines contribute to innate immunity by other mechanisms, like inducing inflammation on the site of infection and recruiting other inflammatory cells to infected tissues." (PMID 24804732, 2014).
infection (continued). "Higher mRNA expression levels of IL-1β, MCP-1, and TNF-α have been demonstrated in the alveolar macrophages (AMs) of diabetic patients that failed to control infection in contrast to normal AMs." (PMID 24223208, 2013). "Levels of IL-1β produced by RAW and MH-S macrophages were independent of infection and no detectable differences in IL-1β secretion were observed between infected and not infected cells." (PMID 23633954, 2013). "Here we observed that, in the presence of WT RIG-I protein, there was a significant upregulation of the IL-1β response to IAV PR8 (similar results were obtained upon USSR infection, data not shown) compared to cells transfected with the empty vector." (PMID 23592984, 2013). "The release of IL-1β and IL-8 (data not shown), were inhibited in the presence of the anti-ICAM-1 antibody showing that infection of NHBE cells by HRV14 was required to trigger a measurable cytokine release." (PMID 23723976, 2013). "While in cultured dendritic cells NLRP3 was crucial for IL-1β secretion in a T4SS-dependent/CagA-VacA-independent manner, this NLR did not play a role during murine infection." (PMID 24381573, 2013). "Given the results of the present study, it seems more likely that the CNS inflammatory response to acute inflammatory events elicited by infection, surgery or trauma, is being driven by TNF-α or IL-1β, rather than IL-6." (PMID 23840908, 2013). "It was recently reported that infection of murine monocytic cells with an influenza virus lacking PB1-F2 (ΔPB1-F2) induced higher levels of IL-6 and IL-1β than with the wt virus." (PMID 23704945, 2013). "Expression of TNFα, IL1b, IFNγ, TGFβ and IL10 was still significantly upregulated in the infected animals compared to the non-infected 7 days after infection." (PMID 22815907, 2012). "In contrast to the cytokine expression in WT mice, the expression of IL-1β and TNF-α in STAT3 KO mice was not longer raised 28 days after infection." (PMID 22675647, 2012). "Compared to the infected wild-type mice, the mRNA expression levels of IL-1β, IL-6, and TNF-α as well as the number of infiltrating immune cells revealed no distinction in STAT3 KO mice 10 days after infection." (PMID 22675647, 2012). "Gastric epithelial MKN7 cells produced the pro-inflammatory cytokines IL-6 and IL-8, but not IL-1β, IL-10, IL-12p70 or TNF (data not shown), after infection with H. pylori J99." (PMID 22563496, 2012). "Estimated frequencies of IL1B, TNF and IL6 two-locus (SNP) haplotypes in patients with prosthetic joint infection after total joint arthroplasty (TJA with PJI), those without infection (TJA without PJI) and Czech healthy controls." (PMID 22568934, 2012). "ATP treatment also increased IL-1β secretion in BMDM after a 6 hours (but not 24 hours) infection with live CP; but BMDM treated with UVCP for 24 hours and then challenged with ATP did not secrete IL-1β." (PMID 21731762, 2011). "Transcription of il6, tnf, il10, mip2, and kc was strongly upregulated upon infection in the presence of XIAP, while induction of ifnb, il1b, ido, and inos was not significantly altered." (PMID 18769721, 2008). "It would be interesting to evaluate in those murine models of Gram-negative pathogens infections whether the CRL1505 or CRL1506 strains can also modulate the levels of CSF3, IL-1β, IL-12, CSF2, CCL2, CCL8, and adhesion molecules as we observed in this work." (PMID 40141330, 2025). "When we examined the expression levels of inflammatory cytokines and interferons, we found that the expression levels of interleukin-1 beta (IL-1β), interleukin-6 (IL-6), tumor necrosis factor (TNF-α), interferon beta (IFN-β), and interferon lambda-1 (IFN-λ1) were not altered by MPXV infection." (PMID 41542170, 2025). "Also, a strong and positive correlation emerged between the synovial levels of IL-1β and PTX3 (Spearman r = 0.67, p = 0.004) that was lost in the absence of infection." (PMID 38790226, 2024).